CR1 (complement C3b/C4b receptor 1 (Knops blood group))
Description:
Membrane immune adherence receptor that plays a critical role in the capture and clearance of complement-opsonized pathogens by erythrocytes and monocytes/macrophages. Mediates the binding by these cells of particles and immune complexes that have activated complement to eliminate them from the circulation. Also acts in the inhibition of spontaneous complement activation by impairing the formation and function of the alternative and classical pathway C3/C5 convertases, and by serving as a cofactor for the cleavage by factor I of C3b to iC3b, C3c and C3d,g, and of C4b to C4c and C4d. Also plays a role in immune regulation by contributing, upon ligand binding, to the generation of regulatory T cells from activated helper T cells. (Microbial infection) Acts as a receptor for Epstein-Barr virus.
Synonyms: CD35; C3BR; KN; C4BR
Tractability: Antibody: its Gene Ontology location is reachable by antibodies, with high confidence; UniProt predicts a signal peptide or a membrane-spanning region; the Human Protein Atlas places it where antibodies can reach. PROTAC: ubiquitination databases record sites on it. Other modalities: a drug acting on it is in phase 2 or 3 trials.
Target class: Membrane receptor
Gene: Protein-coding gene on chromosome 1 (207,496,147 to 207,641,776, forward strand). Ensembl gene ENSG00000203710.
Subcellular location: Membrane
Subcellular location (Human Protein Atlas): Plasma membrane
Pathways (Reactome):
Immune System: Neutrophil degranulation; Regulation of Complement cascade
Gene expression (Transcription): RUNX1 and FOXP3 control the development of regulatory T lymphocytes (Tregs)
Gene Ontology:
Molecular function: complement component C3b binding; complement component C3b receptor activity; complement component C4b binding; complement component C4b receptor activity; protein binding; complement binding; complement receptor activity
Biological process: ATP export; complement activation; complement activation, alternative pathway; complement receptor mediated signaling pathway; glomerulus development; immune complex clearance; immune complex clearance by erythrocytes; negative regulation of activation of membrane attack complex; negative regulation of complement activation; negative regulation of complement activation, alternative pathway; negative regulation of complement activation, classical pathway; negative regulation of complement-dependent cytotoxicity; negative regulation of immunoglobulin production; negative regulation of interleukin-2 production; negative regulation of plasma cell differentiation; negative regulation of serine-type endopeptidase activity; negative regulation of T cell proliferation; negative regulation of type II interferon production; organ or tissue specific immune response; plasma membrane organization; positive regulation of activation of membrane attack complex; positive regulation of cell population proliferation; positive regulation of regulatory T cell differentiation; positive regulation of serine-type endopeptidase activity; T cell mediated immunity; and 2 more
Cellular component: cell surface; cytoskeleton; extracellular exosome; membrane; plasma membrane; plasma membrane raft; ficolin-1-rich granule membrane; secretory granule membrane
Genetic constraint (gnomAD): Loss-of-function variants: 93 observed, 142.68 expected, observed/expected ratio (o/e) 0.65, 90% interval 0.55 to 0.77. The synonymous counts are far from expectation, so gnomAD's model fits this gene poorly and the ratio says little. Missense variants: 1,537 observed, 1,753.3 expected, observed/expected ratio (o/e) 0.88, 90% interval 0.84 to 0.91. Synonymous variants: 525 observed, 627.39 expected, observed/expected ratio (o/e) 0.84, 90% interval 0.78 to 0.9.
Homologues: Orthologues: chimpanzee CR1 (81% identical), macaque CR1 (76% identical), rat Cd46 (12% identical), mouse Cr1l (10% identical), guinea pig Crrp (3% identical). Paralogues in human: CR1L (17% identical), CSMD3 (16% identical), CSMD1 (16% identical), CSMD2 (16% identical), SVEP1 (15% identical), CR2 (13% identical), C4BPA (7% identical), SELP (6% identical), SEZ6L (6% identical), CFH (6% identical), SEZ6L2 (5% identical), PAPPA2 (5% identical), and 27 more.
Diseases named in the same sentence as CR1 in open-access papers:
CR1 is named in the same sentence as 226 diseases in open-access papers, as found by Europe PMC text mining. Sharing a sentence is not in itself a finding about the gene and the disease. The quoted sentences say what the papers report.
Alzheimer disease (62 papers, 2010 to 2025). A progressive, neurodegenerative disease characterized by loss of function and death of nerve cells in several areas of the brain leading to loss of cognitive function such as memory and language. "Previous work has even suggested that copy number of the CR1 C3B/C4B binding domain is associated with Alzheimer’s disease risk." (PMID 40502163, 2025). "For example, the Alzheimer’s disease-associated gene, CR1, has a tandem domain duplication that camouflages a large segment of the gene." (PMID 40502163, 2025). "This has the potential to improve the diagnostic toolbox for malaria, SLE and Alzheimer’s disease, in which susceptibility or severity is correlated to low levels of CR1 on RBCs." (PMID 37591894, 2023). "Genome wide association studies (GWAS) have identified Alzheimer’s disease risk single nucleotide polymorphisms (SNPs) in complement receptor 1 (CR1), clusterin (CLU) and C1S." (PMID 35794654, 2022). "In 2009, a genome-wide association (GWA) study identified CR1 as a potential risk factor for Alzheimer’s disease." (PMID 32907542, 2020). "The complement component (3b/4b) receptor 1 gene (CR1) gene has been proved to affect the susceptibility of Alzheimer’s disease (AD) in different ethnic and districts groups." (PMID 32919460, 2020). "Genetic variation in CR1 has been associated with a variety of diseases, such as Alzheimer’s disease, Malaria, and Systemic Lupus Erythematous; however, in many cases the precise genetic variations have not been identified." (PMID 32907542, 2020). "The risk for Alzheimer's disease increases with the preferential, low expression of a long CR1 isoform, which is ineffective in the removal of beta-amyloid plaques." (PMID 31824479, 2019). "Single nucleotide variants (SNVs) within and surrounding the complement receptor 1 (CR1) gene show some of the strongest genome-wide association signals with late-onset Alzheimer’s disease." (PMID 29675612, 2018). "Polymorphism in the CR1 gene, encoding the complement component (3b/4b) receptor 1, is associated with development of Alzheimer’s disease, likely because CR1 is involved in β-amyloid clearance." (PMID 25120903, 2014). "Large-scale genome-wide SNP association studies have identified an association between variants of CR1, the gene encoding complement component receptor 1, and the sporadic form of Alzheimer's disease." (PMID 23153828, 2013). "Regarding CR1 polymorphisms, studies have shown the association of CR1 gene polymorphisms with various diseases such as Alzheimer's disease, systemic lupus erythematosus (SLE), lower erythrocyte sedimentation rate, spontaneous idiopathic preterm birth, cancer, and infectious diseases." (PMID 37833411, 2023). "The exact nature of the association of CR1 with Alzheimer’s disease is not well understood." (PMID 32907542, 2020). "Genome-wide association studies (GWAS) in Alzheimer's Disease (AD) have identified polymorphisms in two other genes encoding proteins associated with the complement system, complement receptor 1 (CR1; CD35) and clusterin, that independently influence risk of developing AD." (PMID 22749446, 2012). "Polymorphisms in CR1 (CD35) are discussed to play a role in cerebral amyloid angiopathy, which is a leading cause in intracerebral hemorrhage and might even be associated with the risk of Alzheimer's disease." (PMID 25537509, 2015). "Four DMRs in Braak III vs. Braak 0 fell within dark regions of Alzheimer's disease risk genes (ABACA7, AMY1A, CHRFAM7A, CR1)." (PMID 41235755, 2025). "In the case of Alzheimer’s disease, CR1 and APOC1 appeared to have Tier A evidence of effects, in line with existing literature implicating them in the aetiopathogenesis of condition." (PMID 40281223, 2025). "The use of TADs through the HiC assay in Alzheimer’s disease would leave the analysis blind to any physical interactions or GWAS SNPs with this region of CR1 and it would increase the complexity of TAD boundary identification." (PMID 40502163, 2025).
Alzheimer disease (continued). "The second study also identified CLU as well as CR1 in a total discovery and replication sample of 14,636 subjects (6010 cases, 8625 controls) from the European Alzheimer’s Disease Initiative (EADI)." (PMID 34935119, 2022). "Given the current focus on developing treatments for Alzheimer’s disease, we expect the B6.CR2CR1 model to be a key resource to advance our understanding of how CR1 risk alleles contribute to disease susceptibility." (PMID 32907542, 2020). "For the CD46 locus, we found significant association corrected for multiple testing (false-discovery rate, FDR < 5%) for schizophrenia (in CD46 and CR1L) and for Alzheimer’s disease (in CR1)." (PMID 32843070, 2020). "Another study identified specific CR1 SNPs (rs6656401 and rs4844609) that influenced rate of cognitive decline in Alzheimer’s disease in combination with APOE status." (PMID 32907542, 2020). "CR1 is a top Alzheimer’s disease gene that plays a critical role in the complement cascade as a receptor for the C3b and C4b complement components, and potentially helps clear amyloid-beta (Aβ)." (PMID 31104630, 2019). "Representative examples are triggering receptor expressed on myeloid cells-2 (Trem2), Cd33, Cr1, Mef2c, members of the MS4A family, and the HLA locus, which are Alzheimer’s disease (AD) risk genes." (PMID 31627485, 2019). "CR1 is another dark gene that is 26.5% dark CDS, being camouflaged to itself, and is strongly implicated in Alzheimer’s disease." (PMID 31104630, 2019). "Previous evidence suggest involvement of the complement receptor 1 (CR1) in development of Alzheimer’s disease." (PMID 29212848, 2018). "Copy number variations in the 54.7 kb STR of CR1 have been associated with SLE and Alzheimer's disease (ALZ)." (PMID 24988487, 2014). "First, this observation provides a better understanding of the immune system’s involvement in Alzheimer’s disease, which involves the gene for complement receptor 1 (CR1)." (PMID 24663666, 2014). "Further elucidation of the role of Crry/CR1 in brain will doubtless contribute to our better understanding of the Alzheimer's disease process." (PMID 23153828, 2013). "The minor allele of a variant in the complement receptor 1 (CR1) gene, Ser1610Thr (rs4844609), which has a population frequency of 0.02, is associated with episodic memory decline and susceptibility to Alzheimer disease." (PMID 23820649, 2013). "Amongst the associations identified by this less stringent approach were those for brain levels of CLU, CR1 and GAB2 which were identified as risk loci in GWAS of Alzheimer's disease." (PMID 22685416, 2012). "Recent genome-wide association studies of Alzheimer's disease (AD) have identified variants in BIN1, CLU, CR1 and PICALM that show replicable association with risk for disease." (PMID 21347408, 2011). "Recently, two large genome wide association studies in Alzheimer disease (AD) have identified variants in three different genes (CLU, PICALM and CR1) as being associated with the risk of developing AD." (PMID 20209083, 2010). "Because of the increasing overlap described between prion and Alzheimer's diseases we also chose Clu, Picalm and Cr1, which were identified as part of Alzheimer's disease GWAS." (PMID 21151910, 2010). "Study of miRNA involvement in Alzheimer’s disease pathogenesis is relevant, since the associations of protein-coding genes (APOE4, ABCA7, BIN1, CLU, CR1, PICALM, TREM2) with the disease revealed as a result of GWAS make it difficult to explain its complex pathogenesis." (PMID 38680184, 2024). "The CR1 gene is particularly notable given that CR1 is a top-ten Alzheimer’s disease gene." (PMID 31104630, 2019). "Recent studies showed that CR1 mRNA could be detected in the cortex and cerebellum of Alzheimer's disease (AD) patients but in very low amounts." (PMID 31011487, 2019).
Alzheimer disease (continued). "Because CR1 is a top-10 Alzheimer’s disease gene, we then specifically interrogated it using our method for any functional mutations that could be involved in Alzheimer’s disease." (PMID 31104630, 2019). "As a proof of concept, we applied our method to the Alzheimer’s Disease Sequencing Project (ADSP) data and identified a rare, ten-nucleotide frameshift deletion in the C3b and C4b binding domain of CR1, a top Alzheimer’s disease gene, that is present in five ADSP cases but zero controls." (PMID 31104630, 2019). "The complement receptor 1 (CR1) gene was shown to be involved in Alzheimer’s disease (AD)." (PMID 30044434, 2018). "The role of CR1 and the complement system in Alzheimer's disease remains far from clear." (PMID 23153828, 2013). "Genetic studies including genome-wide studies have also associated inflammation-related genes to the etiology of Alzheimer’s disease (i.e. ABCA7, CLU, CR1, HLA-DRB1, HLA-DRB5, PICALM, and TREM2), further supporting the concept of neuroinflammation as a pathogenic factor in Alzheimer’s disease." (PMID 34335238, 2021). "While we could not formally assess the association of the CR1 frameshift mutation with Alzheimer’s disease due to insufficient sample-size, we believe it merits investigating in a larger cohort." (PMID 31104630, 2019). "The importance of neuroinflammation and microglia in Alzheimer’s disease has been highlighted by multiple GWAS, which have identified a number of single polymorphisms associated with risk for development of Alzheimer’s disease in several immune related genes, including TREM2, CD33, BIN1, and CR1." (PMID 31504240, 2019). "With CR1 being a top Alzheimer’s disease gene without any known functional mutations, we believe it will be important to assess this mutation in a large cohort, to determine whether it plays a role in disease development and progression." (PMID 31104630, 2019). "With the Alzheimer’s Disease Neuroimaging Initiative (ADNI) database, previous studies have investigated the correlation between 15 ABCA7 and 83 CR1 SNPs and CSF biomarkers." (PMID 34958020, 2022). "Here, we present a new mouse model expressing the human proteins CR1 and CR2 that will be of value to study of an array of human diseases including Alzheimer’s disease, Systemic Lupus Erythematosus and infections such as malaria." (PMID 32907542, 2020). "Our results strongly suggest the active roles of C7, together with other complement components such as the GWAS hits CR1, CLU and CFH, in the development of Alzheimer's disease." (PMID 31032141, 2019). "Using our PRT and junction fragment PCR approaches, we typed a case–control cohort of early-onset Alzheimer’s disease and a case–control cohort of late-onset Alzheimer’s disease for copy number of the LCR within the CR1 gene, inferring the CR1-B genotype." (PMID 29675612, 2018). "We rescue a rare ten-nucleotide frameshift deletion in CR1, a top Alzheimer’s disease gene, found in disease cases but not in controls." (PMID 31104630, 2019). "This method will enable researchers to carry out genetic polymorphism studies for genetic risk factors associated with late-onset Alzheimer’s disease (BIN1, CLU, ABCA7, CR1 and PICALM) without the use of expensive instrumentation and reagents." (PMID 23419238, 2013). "However, a transgenic mouse expressing CR1 in mouse erythrocytes exists, and a new model with a human CR1/CR2 knock in created by the MODEL-AD consortium may eventually enable a better understanding of the role of this regulatory protein in protection from Alzheimer’s disease." (PMID 33239010, 2020).
malaria (62 papers, 2005 to 2025). Malaria is a serious and sometimes fatal disease caused by a parasite that commonly infects a certain type of mosquito which feeds on humans. "The role of CR1 density polymorphisms in malaria susceptibility is complex and appears to be highly dependent on the epidemiological context." (PMID 41450567, 2025). "Along the Sino-Burmese border in Yunnan Province, the CR1 variants 3093 T and 520 T, which are associated with reduced CR1 expression on erythrocytes, have been identified as region-specific polymorphisms linked to malaria prevalence." (PMID 40993672, 2025). "Consistently, genome-wide analyses have identified a novel CR1 variant, rs12034598, under positive selection in other malaria-endemic populations." (PMID 40993672, 2025). "We identified several candidates through population and regional-specific analyses, including the CR1 gene, which is associated with immunity and Malaria resistance, and other genes involved in metabolic evolution." (PMID 38665582, 2024). "Genetic variations in CR1 lead to CR1 deficiency, which occurs in regions with high incidences of Malaria, yet this mechanism can prevent severe Malaria." (PMID 38665582, 2024). "Further gene enrichment, the allele frequency distribution of derived alleles, and their correlation with the incidence of Malaria further confirmed that CR1 played an essential role in the resistance of Malaria in the ancient "Baiyue" tribes." (PMID 38665582, 2024). "The heterozygote (L/H) of rs2274567 was associated with intermediate CR1 expression levels and protection against severe malaria in populations from the highly endemic region of Papua New Guinea." (PMID 36626386, 2023). "Such variants of CR1 were reported to be under selection in populations living in Sardinia or prevalent in other malaria-endemic regions such as Papua New Guinea, India, and Kenya." (PMID 36173765, 2022). "For example, CR1 plays a key role in the Knops blood group on erythrocytes; the CR1 polymorphisms can result in the CR1 deficiency and help confer protection against severe malaria." (PMID 36173765, 2022). "Erythrocyte CR1 deficiency is common in some malaria-endemic countries such as Papua New Guinea and India, and is associated with protection against severe malaria in medium to high transmission areas." (PMID 31455446, 2020). "CR1 has been implicated in the pathogenesis of multiple diseases, with epidemiological and in vitro data suggesting a role in malaria." (PMID 29690995, 2018). "Our study highlights that the loss of CRPs in both species of malaria is particularly apparent in uninfected RBCs, whereas infected RBCs of both P. falciparum and P. vivax malaria have higher expression of CR1, CD55, and CD59 than uninfected RBCs." (PMID 30429373, 2018). "In sub-Saharan African populations, two neighbouring polymorphisms in the Complement Receptor One (CR1) gene, named Sl2 and McCb, occur at high frequencies, consistent with selection by malaria." (PMID 29690995, 2018). "Although several studies have attempted to determine the association of CR1 polymorphisms with severe malaria, observations remain inconsistent." (PMID 23152904, 2012). "A total of 3 studies were examined for association of CR1 polymorphisms (both exon 22 and intron 27) and severe malaria." (PMID 23152904, 2012). "Since both polymorphisms of CR1 were associated with protection against severe malaria, we analysed the distribution of CR1 haplotypes in different clinical categories to study their probable association." (PMID 23152904, 2012). "Meta-analysis revealed that the CR1 exon 22 low expression polymorphism is significantly associated with protection against severe malaria." (PMID 23152904, 2012). "Association of common functional polymorphisms at CR1 genes with severe malaria have been studied in various populations." (PMID 23152904, 2012). "Several studies have investigated the association of common functional variants of CR1 with severe malaria." (PMID 23152904, 2012).